FAM53C (family with sequence similarity 53 member C)
Synonyms: C5orf6; LOC100128966
Tractability: PROTAC: ubiquitination databases record sites on it.
Gene: Protein-coding gene on chromosome 5 (138,331,935 to 138,349,729, forward strand). Ensembl gene ENSG00000120709.
Gene Ontology:
Molecular function: protein binding
Biological process: protein import into nucleus
Cellular component: nucleus
Genetic constraint (gnomAD): Loss-of-function variants: 10 observed, 36.64 expected, observed/expected ratio (o/e) 0.27, 90% interval 0.17 to 0.46. The upper end of that interval is the gene's LOEUF score, 0.46, which puts it in group 2 of 6, group 1 being the genes least tolerant of losing a copy. Missense variants: 442 observed, 539.29 expected, observed/expected ratio (o/e) 0.82, 90% interval 0.76 to 0.89. Synonymous variants: 203 observed, 214.01 expected, observed/expected ratio (o/e) 0.95, 90% interval 0.85 to 1.07.
Homologues: Orthologues: chimpanzee FAM53C (99% identical), macaque FAM53C (99% identical), rabbit FAM53C (98% identical), guinea pig FAM53C (97% identical), mouse Fam53c (95% identical), rat Fam53c (94% identical), pig FAM53C (91% identical), dog FAM53C (88% identical), zebrafish fam53c (34% identical). Paralogues in human: FAM53A (30% identical), FAM53B (27% identical).
Diseases named in the same sentence as FAM53C in open-access papers:
FAM53C is named in the same sentence as 8 diseases in open-access papers, as found by Europe PMC text mining. Sharing a sentence is not in itself a finding about the gene and the disease. The quoted sentences say what the papers report.
Down syndrome (2 papers, 2023 to 2026). "The identification of FAM53C as a suppressive binding partner for DYRK1A sheds new light on the molecular mechanism of Down syndrome caused by triplication of DYRK1A in human chromosome 21." (PMID 37802655, 2023). "Because DYRK1A dysregulation contributes to developmental disorders such as Down syndrome as well as tumorigenesis, future strategies aiming at regulating FAM53C activity may benefit a broad range of patients." (PMID 42059432, 2026). "A previously uncharacterized protein, FAM53C, is identified as a binding partner for the kinase DYRK1A involved in numerous neurodevelopmental disorders, such as Down syndrome and autism spectrum disorder." (PMID 37802655, 2023).
Alzheimer disease (1 paper, 2023). A progressive, neurodegenerative disease characterized by loss of function and death of nerve cells in several areas of the brain leading to loss of cognitive function such as memory and language. "FAM53C, by suppressing DYRK1A activity, may possibly also be involved in Alzheimer disease." (PMID 37802655, 2023).
breast carcinoma (1 paper, 2020). "Another established breast cancer prognostic miRNA, hsa-mir-1290, was down-regulated (logFC −0.58) TNCB samples and target critical genes such as SGOL1, a member of Shougoshin family member, FAM53C and transcription factor II-I GTF21." (PMID 32182819, 2020).
COVID-19 (1 paper, 2025). A disease caused by infection with severe acute respiratory syndrome coronavirus 2. "Our analysis of the cis-eQTL effects of the SNP rs1042665 HSPA9 suggests a complex interplay of gene regulation involving KDM3B, ETF1, FAM53C, KLHL3, and DNAJC18, potentially contributing to COVID-19 severity." (PMID 41009536, 2025).
Hypertension (1 paper, 2013). The presence of chronic increased pressure in the systemic arterial system. "Among the highly up-regulated genes in the MCA of the hypertension only group compared to sham controls were FAM167A, CERS3 and FAM53C." (PMID 23874591, 2013).
cancer (1 paper, 2026). A tumor composed of atypical neoplastic, often pleomorphic cells that invade other tissues. "Here, using data from the Cancer Dependency Map, we identified FAM53C as a new regulator of cell cycle progression." (PMID 42059432, 2026).
FAM53C also shares sentences with these, for which no sentence is quoted: autism spectrum disorder (1 paper); neurodevelopmental disorder (1).